TSPAN8 (tetraspanin 8)
Diseases named in the same sentence as TSPAN8 in open-access papers (continued):
Sharing a sentence is not in itself a finding about the gene and the disease.
melanoma (continued). "Finally, we evaluated the Tspan8 expression level in patient melanomas by immunohistochemistry according to the ZEB1 expression level, between ZEB1high, ZEB1int, and ZEB1low melanomas, in a cohort of 18 patient samples." (PMID 38398085, 2024). "We therefore questioned whether Tspan8 could mediate EMT-TFs’ effect on the biomechanical and morphological properties of melanoma cells." (PMID 38398085, 2024). "Our own data indicate that melanoma cells in the epidermis, even when presenting an invasive potential due to Tspan8, do not express proMMP-9." (PMID 32455575, 2020). "Finally, we observed a tumor-promoting effect of Tspan8 in vivo and a mutually exclusive expression pattern between Tspan8 and phosphorylated ILK in melanoma xenografts and human melanocytic lesions." (PMID 28188308, 2017). "In conclusion, melanoma cell-matrix anchorage was mainly regulated by β1 integrins, and Tspan8-weakened β1-dependent adhesiveness was not mediated by variations in the cell surface repertoire or protein levels of integrin subunits." (PMID 28188308, 2017). "We previously identified Tetraspanin 8 (Tspan8) as a critical mediator of melanoma invasion, whose expression is absent in healthy skin." (PMID 28188308, 2017). "Thus, our study identified Tspan8 as a novel regulator of ILK-driven β1 integrin signaling, mediating low interactions of melanoma cells with the surrounding extracellular microenvironment, mandatory for tumor escape." (PMID 28188308, 2017). "P-ILK staining was observed in benign nevi, although with variable intensity (strong: 9/13; weak 4/13), but never detected in primary melanomas, demonstrating a mutually exclusive expression of Tspan8 and P-ILK." (PMID 28188308, 2017). "The reduced expression of TSPAN8 in invasive melanoma cells did not alter cell viability, as evaluated by XTT assay." (PMID 21081927, 2011). "Immunohistochemistry revealed that TSPAN8 was expressed by melanoma cells in primary melanomas and metastases, but not epidermal cells in healthy skin." (PMID 21081927, 2011). "Flow cytometry of well-defined melanoma cell lines confirmed that TSPAN8 was exclusively expressed by invasive, but not non-invasive melanoma cells or normal melanocytes." (PMID 21081927, 2011). "Among them, TSPAN8, a tetraspanin not yet described in melanoma, was upregulated at mRNA and protein levels in melanoma cells from the invasive clone, as assessed by RT–PCR, flow cytometry and western blot analysis." (PMID 21081927, 2011). "Consistent with the in vitro findings, TSPAN8 was also expressed by melanoma cells in primary tumours and lymph node metastases, but not in healthy epidermis." (PMID 21081927, 2011). "We accordingly found that inducing melanoma EMT switching by overexpressing the ZEB1 transcription factor, a major regulator of melanoma cell plasticity, was sufficient to decrease cell stiffness and transcriptionally induce tetraspanin-8-mediated dermal invasion." (PMID 38398085, 2024). "Although the implication of Rictor in melanoma cells awaits further studies, we clearly demonstrate that in the absence of Tspan8, ILK-dependent Akt-S473 phosphorylation in response to ligation of β1 integrins occurs efficiently, leading to integrin clustering." (PMID 28188308, 2017). "Moreover, Tspan8 promotes in vivo orthotopic tumor growth and an inverse pattern of Tspan8 and P-ILK expression was observed in melanoma xenografts as well as in human melanocytic lesions, underscoring the ability of Tspan8 to modulate ILK function in cutaneous microenvironment." (PMID 28188308, 2017). "Unlike carcinomas where Tspan8 is expressed in normal cells and upregulated in tumor cells, Tspan8 is absent at the mRNA and protein levels in normal melanocytes and non-invasive melanoma cell lines, whereas it is strongly expressed in melanoma cells from a panel of invasive cell lines." (PMID 28188308, 2017).
melanoma (continued). "Interestingly, Tspan8 ablation significantly affected ILK activation in melanoma cells adhering to the matrix but not FAK autophosphorylation." (PMID 28188308, 2017). "The fact that Tspan8 expression interfered only with Akt-S473 and not with Akt-T308 phosphorylation suggests that Tspan8 restricts full Akt activity in melanoma cells through inappropriate ILK activation, leading to attenuation of β1-integrin adhesive function." (PMID 28188308, 2017). "Interestingly, TSPAN8 was not constitutively expressed by normal melanocytes, in contrast to nevocytes and melanoma cells from primary and metastatic lesions." (PMID 21081927, 2011). "Therefore, the cell surface expression of TSPAN8, but not that of CAPG, was associated with the invasive behaviour of a panel of melanoma cells in culture." (PMID 21081927, 2011). "Importantly, T1C3 transfected with scramble or TSPAN8-specific siRNA and untransfected cells all formed compact spheroids that increased in size over 3 days, corroborating the finding that TSPAN8 is not required for melanoma growth." (PMID 21081927, 2011). "Strikingly, melanoma cells were unable to cross the DEJ when keratinocytes were not incorporated, regardless of their Tspan8 expression levels, even after 5 weeks of culture (not shown)." (PMID 32455575, 2020). "TSPAN8 should be considered as a promising target to fight not only aggressive CRC tumors, but also a broad range of other cancer types, such as melanoma, glioma, hepatocellular carcinoma, ovarian and gastric cancers." (PMID 28423546, 2017). "Overall, our data show that Tspan8+ melanoma cells surrounded by keratinocytes maintained lower TIMP-1 level when compared to melanoma cells juxtaposed without contacts with keratinocytes, thus favoring proMMP-9 activation by the fully active MMP-3, in a Tspan8-dependent manner." (PMID 32455575, 2020). "The correlation between TSPAN8 expression and aggressiveness was not restricted to our melanoma model, as SKMel28 and WM793 melanoma cell lines, chosen because they are able to invade dermis in human skin reconstructs, also expressed TSPAN8 on their cell surface." (PMID 21081927, 2011).
pancreatic adenocarcinoma (14 papers, 2014 to 2024). "Examination of exosomes from pancreatic adenocarcinoma cells revealed the presence of tetraspanin 8 in these vesicles." (PMID 39031113, 2024). "Recently conducted research revealed that tetraspanin 8 is a protein that can be used in the development of CAR‐T therapy for pancreatic adenocarcinoma, together with new identified targets CD66c and CD318." (PMID 39031113, 2024). "Investigation of the function of tetraspanin 8 in pancreatic adenocarcinoma suggests that this protein is overexpressed in cancer stem cells." (PMID 39031113, 2024). "Some recent reports showed that TSPAN8 regulates cell proliferation, invasion and metastasis in various types of tumours, including pancreatic adenocarcinoma." (PMID 34498099, 2021). "Their function can be inferred by the evidence that expression of tetraspanin 8 (Tspan8) causes modifications of transmembrane proteins (VCAM-1, α4 integrin) in the exosome content of a rat pancreatic adenocarcinoma cell line." (PMID 31450727, 2019). "Tspan8 and CD151 are metastasis-promoting tetraspanins and a knockdown (kd) of Tspan8 or CD151 and most pronounced of both tetraspanins affects the metastatic potential of the rat pancreatic adenocarcinoma line ASML." (PMID 25544774, 2015). "This feature becomes of particular interest for tetraspanins that are engaged in metastasis formation, which is well known for CD151 and Tspan8, the latter also being a CIC marker in pancreatic adenocarcinoma." (PMID 25544774, 2015). "In contrast, EVs derived from the highly metastatic rat pancreatic adenocarcinoma line BSp73ASML, which are enriched, in α6β4 and tetraspanins CD151 and Tspan8, preferentially target lung and lymph node stroma cells." (PMID 25278937, 2014). "In vitro, TEX of a Tspan8 overexpressing non-metastatic rat pancreatic adenocarcinoma (PaCa) line (AS-Tspan8) promotes EC progenitor maturation, expansion, and activation." (PMID 32013145, 2020).
lung carcinoma (13 papers, 2019 to 2025). "CD151, CD171, and tetraspanin 8 represent very reliable markers for lung cancer characterization and identification." (PMID 38893088, 2024). "Three membrane proteins, CD151, CD171 and TSPAN8, on the sEVs derived from lung cancer tissues can be used to distinguish different pathological types of lung cancer." (PMID 34094979, 2021). "We successfully identified epistasis in RGL1:RAD51B in ALL and NSCLC lung cancer, SYNE1:RNF43 in ADE and FHIT:TSPAN8 in SQC risk development." (PMID 30956756, 2019). "For FHIT:TSPAN8 gene pair identified from SQC cohort, individuals with genotype 0/1 had a significant reduced lung cancer risk with OR 0.63 and p value 9.15x10-6." (PMID 30956756, 2019). "They found that CD151, CD171 and tetraspanin 8 were the most effective biomarkers for distinguishing between those with and without lung cancer, as well as differentiating between various types of lung cancer histology." (PMID 37641132, 2023). "Interestingly, all the three significant epistasis—-RGL1:RAD51B in ALL and NSCLC lung cancer, SYNE1:RNF43 in ADE and FHIT:TSPAN8 in SQC risk development—-were displayed as interaction between networks." (PMID 30956756, 2019). "Additionally, CD151, CD171, and tetraspanin 8 were important markers to distinguish patients with all histology lung cancer from cancer-free individuals thus highlighting promising use of exosomes in lung cancer diagnosis." (PMID 39464709, 2024). "Additionally, CD171, CD151, and tetraspanin-8 (Tspan8) could also be differentiated for lung cancer patients, both NSCLC and SCLC, compared to controls." (PMID 34830787, 2021). "The Extracellular Vesicle Array (EV Array) to phenotype lung cancer-related proteins in plasma exosomes may be a simple, minimal invasive tool, by which exosomal proteins CD151, CD171 and tetraspanin 8 are found to be higher in lung cancer patients of all histological subtypes." (PMID 33504342, 2021). "In patients with unclear tissue subtypes of lung cancer, the AUC of detection of CD151 was 0.68, CD171, 0.61, and TSPAN8, 0.60." (PMID 34094979, 2021). "CD151, CD171, and TSPAN8 were concluded to be promising exosomal biomarkers for distinguishing patients with lung cancer from patients without cancer." (PMID 35158999, 2022). "The exosomal markers CD151, CD171, and tetraspanin 8 were identified as the strongest differentiators of patients with lung cancer of all histological subtypes from patients without lung cancer." (PMID 34281588, 2021).
type 2 diabetes (12 papers, 2008 to 2021). "Previous genome-wide association studies identified TSPAN8 loci, which was correlated with an increased risk of type 2 diabetes (T2D) in humans." (PMID 34016141, 2021). "We identified fourteen type 2 diabetes-associated genes discovered by the first waves of GWAS for which there was little prior evidence of their potential role in diabetes (Adam30, Adamts9, Camk1d, Cdc123, Cdkal1, Cdkn2a, Cdkn2b, Ext2, Hhex, Ide, Jazf1, Lgr5, Thada and Tspan8)." (PMID 23442068, 2013). "Just 3 susceptibility loci among the four diseases were identified; TSPAN8 in type 2 diabetes, IRGM in CD and the HLA region in T1D, RA and CD, all of which had previously been identified." (PMID 22654554, 2011). "In the Inter99 study the type 2 diabetes risk alleles in the region between the CDC123 and the CAMK1D and in the TSPAN8 locus associated with a range of OGTT-based surrogate measures of serum insulin release." (PMID 19789630, 2009). "A very recently published study investigated associations of the type 2 diabetes risk alleles in JAZF1, CDC123/CAMK1D, TSPAN8/LGR5, THADA, ADAMTS9, and NOTCH2 with obesity, insulin sensitivity, and insulin secretion in 4516 Danes." (PMID 18714373, 2008). "However, it is not unexpected that our study was unable to find significant associations between SNPs in JAZF1, CDC123/CAMK1D, TSPAN8/LGR5 and ADAMTS9 and type 2 diabetes, since the meta-analysis required more than 9000 samples for an 80% power." (PMID 20161779, 2010). "Furthermore, a meta-analysis of three GWASs detected six novel variants (in JAZF1, CDC123/CAMK1D, TSPAN8/LGR5, THADA, ADAMTS9, and NOTCH2) that were associated with type 2 diabetes." (PMID 20161779, 2010). "For example, microarray studies performed on human pancreatic islets isolated from patients with type 2 diabetes and glucose-tolerant controls identified, among other changes, overexpression of ENPP1, TSPAN4, TSPAN8, CSRP1, REG3A and REG3G, genes that were also upregulated with age in our study." (PMID 26699651, 2016). "The copy numbers of studies for risky genes in type-2 diabetes patients have shown that epidermal growth factor receptor (EGFR), E2F transcription factor 1 (E2F1), protein phosphatase 1 regulatory subunit 3A (PPP1R3A), human leukocyte antigen (HLA), and tetraspanin 8 (TSPAN8) are important." (PMID 34563047, 2021). "TSPAN8, as well as TSPAN proteins co-regulated by TSPAN8 (identified in the transcriptional profling experiments above) could all serve as potential therapeutic strategies for Type 2 Diabetes." (PMID 23840313, 2013).
colon carcinoma (11 papers, 2012 to 2025). "Compared with normal adjacent tissues to cancer (NATs), the mRNA level of Tspan8 in pancreatic ductal adenocarcinoma, colon cancer, hepatocellular carcinoma, prostate cancer, rectal cancer, and gastric cancer is significantly increased." (PMID 38649381, 2024). "High expression of Tspan8 was restricted to the colon carcinoma cell line HT29, while low to medium expression was detectable in IGROV-1, LOX and Huh7, reflecting the cancer genome data." (PMID 36078095, 2022). "This strategy is consistent with recent data identifying Tspan8 as a blood biomarker candidate for early detection of human colon cancer, and demonstrating that Tspan8-specific antibodies reduce the incidence of ovarian cancer metastasis." (PMID 28188308, 2017). "Conversely, Tspan8 silencing attenuated the migration of colon cancer cells and upregulated calcium-dependent cell-cell aggregation." (PMID 28188308, 2017). "Ectopic expression Tspan8 in Isreco colon cancer cell line stimulated cell motility through cooperation with the E-cadherin/p120-catenin membrane complex." (PMID 28188308, 2017). "Interestingly, by using Tspan8-deficient HT29 colon carcinoma cells, we observed that while Tspan8 promoted cleavage of the ADAM17 substrate TNF α, it did not alter ADAM17-mediated shedding of TNFR1." (PMID 36078095, 2022). "TSPAN8, promotes cell-to-cell communication by regulating integrins and other cell surface proteins, and its expression has been correlated with metastasis and worse prognosis in colon cancer where it contributes to cell motility through a complex with E-cadherin." (PMID 30100995, 2018). "A mixture of TSPAN8 antibody-conjugated NIR-SERRS dots was applied to HCT8 cells in vitro and intravenously administered to human colon cancer-bearing mice." (PMID 39934124, 2025). "This was observed by transduction of the colon carcinoma cell line Isreco1, which does not express Tspan8, and on ileum tissue fragments of tspan8ko mice versus wild type mice." (PMID 37835445, 2023). "Immunoblotting results showed that expression of CAM molecules, such as claudin-1, −3 and −4, EpCAM, E-cadherin, and Tspan8 were very low in normal colon cancer cell line CCD18Co compared to Caco-2, DLD-1 and SW620 colon cancer cell lines but no expression was observed in DLD-1 cells for Tspan8." (PMID 30289336, 2019).
gastric cancer (10 papers, 2017 to 2024). A primary or metastatic malignant neoplasm involving the stomach. "The expression of TSPAN8 is increased both at the mRNA and protein levels in gastric cancer tissues and is associated with poor survival." (PMID 32138170, 2020). "For example, one study reported that in gastric cancer, TSPAN8 expression in exosomes showed a positive effect on cell growth and invasion." (PMID 38275818, 2024). "Up‐to‐date analyses indicate that the expression of tetraspanin 8 was increased in gastric cancer cells compared with healthy tissues." (PMID 39031113, 2024). "Proteomic analyses have also indicated another potential pathway of action for tetraspanin 8 in gastric cancer." (PMID 39031113, 2024). "In gastric cancer, Tspan8 was found to be positively modulated by EGF in a dose- and time-dependent manner, and silencing Tspan8 diminished the effects of EGF on cell proliferation and invasion." (PMID 38389703, 2024). "In vitro studies have shown that overexpression of tetraspanin 8 promotes the ability of gastric cancer cells to invade and proliferate, whereas suppression of its expression has the opposite effect." (PMID 39031113, 2024). "TSPAN8 is overexpressed (on protein and/or mRNA level) in various cancers, including pancreatic, lung, breast, ovarian, colon, liver, and gastric cancers." (PMID 37059365, 2023). "Here, we summarize tetraspanins that enhance the proliferation and invasion of gastric cancer cells, including TSPAN8, CD151, TSPAN1, and TSPAN4." (PMID 34222025, 2021). "Further, ZHU’s lab showed TSPAN8 acts as an oncogene in gastric cancer and promotes gastric cancer cell proliferation and invasion partially through EGFR signaling." (PMID 34222025, 2021). "MiR-324-5p was demonstrated to repress the viability and induce the apoptosis of gastric cancer cells via down-regulating TSPAN8." (PMID 34222025, 2021). "As for gastric cancer, several studies have revealed that TSPAN8 expression is increased in gastric cancer tissues compared to normal tissues." (PMID 34222025, 2021). "TSPAN8 is a pro-drug resistance protein in gastric cancer cells, while the silencing of TSPAN8 enhances the sensitivity of cancer cells to the cisplatin, 5-FU and adriamycin." (PMID 34222025, 2021). "TSPAN8 promotes gastric cancer cell growth and metastasis through the activation of the extracellular-signal-regulated kinase/mitogen activated protein (ERK/MAPK) pathway." (PMID 32138170, 2020). "The knockdown of TSPAN8 attenuates the effects of the EGFR on gastric cancer cell proliferation and invasion." (PMID 32138170, 2020). "Genome-wide microarray analysis identified TSPAN8 as a gene that is significantly upregulated in gastric cancers compared to normal gastric mucosae, suggesting its use as a novel molecular marker for the detection of circulating gastric cancer cells in the peripheral blood." (PMID 38275818, 2024). "Similarly, TSPAN8 overexpression in gastric cancer and nasopharyngeal carcinoma cell lines has been shown to promote cell invasion." (PMID 38275818, 2024). "Researchers hypothesized that tetraspanin 8 may have an effect on gastric cancer through activation of the ERK/MAPK and EGFR/AKT signaling pathways." (PMID 39031113, 2024). "Furthermore, Tspan8 also plays a vital role in enhancing gastric cancer metastasis via activating the EGFR/Akt pathway." (PMID 38389703, 2024). "Overall, TSPAN8 inhibitors may be developed as an adjuvant therapy of gastric cancer to reduce the resistance of cancer cells." (PMID 34222025, 2021). "Moreover, TSPAN8 impairs the sensitivity of gastric cancer cells to chemotherapeutic agents by mediating Wnt/β-catenin activity." (PMID 32138170, 2020). "Indeed, TSPAN8, a member of the tetraspanin superfamily, is greatly overexpressed in several types of cancer, including colorectal, liver, pancreatic, and gastric cancers and this overexpression correlates with a poor differentiation." (PMID 28726765, 2017).